LEP (leptin)
Diseases named in the same sentence as LEP in open-access papers (continued):
Sharing a sentence is not in itself a finding about the gene and the disease.
Hyperinsulinemia (continued). "LVMI and left ventricular diastolic function were probably also influenced by other factors that could not be examined, e.g. hyperinsulinemia or leptin levels." (PMID 35394150, 2022). "Another study in multiple ethnicities also found that compared with European women, South Asian women had strikingly high leptin concentrations, which could not be explained by fat distribution and hyperinsulinism." (PMID 35941672, 2022). "Leptin was 23.95 ± 17.51 ng/mL in those with insulin below the normal range, 31.15 ± 17.20 ng/mL in those whose insulin was within the normal range, and 63.88 ± 7.40 ng/mL in those with hyperinsulinemia." (PMID 29890036, 2018). "OLETFs have elevated blood glucose, plasma insulin, and leptin levels, an effect consistent with the OLETF phenotype and in agreement with other findings, though the exact mechanisms behind hyperinsulinemia are not fully clear." (PMID 37298724, 2023). "Non-fasting serum levels of metabolic hormones, leptin, insulin and cortisol, determined in the five affected patients from the SOPP were within the normal range except in one proband that presented hyperinsulinemia." (PMID 37083980, 2023). "In contrast to the lack of correlation with serum leptin, TNF-α, IL-6, NF-κB and STAT3 activation, hyperinsulinemia in the foz/foz model remained a candidate enhancer of hepatocarcinogenesis." (PMID 30873458, 2016). "Additionally, the observed in vivo effects of metformin in the hyperleptinemic db/db strain may infer that a subset with the PCOS reproductive phenotype characterized by hyperinsulinemia, anovulation, and hyperleptinemia may be more responsive to metformin than those without elevated leptin levels." (PMID 21605417, 2011). "The high values of leptin in CKD are not solely due to kidney failure; other factors, such as inflammation, reduced erythropoietin levels, hyperinsulinemia, the type of dialysis, dialyzer membrane, and diet, may also be involved." (PMID 39062887, 2024).
Hepatic steatosis (301 papers, 2003 to 2026). Steatosis is a term used to denote lipid accumulation within hepatocytes. "The leptin/BMI ratio demonstrated a strong linear association with hepatic steatosis in continuous analysis (β = 48.8 dB/m per unit increase in CAP, 95% CI 30.0-67.6, p < 0.001, R2=0.040)." (PMID 40956476, 2025). "While our leptin-to-BMI ratio analysis confirms leptin’s utility as a continuous biomarker for hepatic steatosis, the clinical application of relative leptin deficiency definitions in screening populations remains complex." (PMID 40956476, 2025). "Despite this apparent paradox, our findings reinforce the potential utility of leptin as a continuous biomarker for hepatic steatosis risk." (PMID 40956476, 2025). "Higher levels of serum leptin were discovered as a risk factor for hepatic steatosis using ROC curve analysis, serving as an independent predictor for fat accumulation in the liver parenchyma." (PMID 38738048, 2024). "Leptin deficiency can lead to hepatic steatosis, whereas excessive leptin can promote hepatitis and fibrosis." (PMID 37753211, 2023). "In human and animal trials, the administration of FGF21 induces weight loss via the leptin pathway and it seems to have favorable effects on lipid and on glucose metabolism and fatty liver disease via decreased lipogenesis and inflammation." (PMID 37685811, 2023). "In contrast, there are observations from ob/ob mice and from patients with leptin deficiency due to biallelic likely pathogenic variants in the leptin gene, in which liver steatosis has also been described." (PMID 35677722, 2022). "This explains the improvement or prevention of hepatic steatosis development in ob/ob mice, linked to leptin administration." (PMID 34209386, 2021). "Here we observed that higher circulating leptin associated with increased serum lipid profile and increased hepatic steatosis as assessed by histology and imaging." (PMID 34249975, 2021). "ERK1 deficiency in leptin deficient mice also conferred partial protection against hepatic steatosis." (PMID 34569651, 2021). "Aberrant leptin signaling has been implicated in non-alcoholic fatty liver diseases (NAFLD) such as hepatic steatosis, hepatitis, and fibrosis." (PMID 33935782, 2021). "Accordingly, hepatic steatosis develops in leptin-deficient animal models, and an inverse link between serum leptin and the degree of steatosis was shown in patients with bariatric surgery." (PMID 32967195, 2020). "Leptin deficiency can lead to hepatic steatosis, and excess leptin can promote hepatitis and fibrosis." (PMID 33324348, 2020). "Our results demonstrate that hepatic steatosis diagnosed by ultrasound and TE in liver transplant recipients is associated with decreased serum adiponectin and increased serum leptin and insulin levels." (PMID 32728230, 2020). "As an example, in db/db leptin-deficient mice, E2f1 knockout was found to prevent hepatic steatosis through crosstalk with key metabolic pathways." (PMID 32701508, 2020). "After chronic alcohol exposure, mice showed leptin deficiency in association with fatty liver disease, and this phenotype was attenuated after external leptin administration." (PMID 33316927, 2020). "In this study, we further analysed the in vivo effects of NP-1 on weight loss, anorectic actions and liver steatosis in the (fa/fa) Zucker model, a context of leptin resistance that promotes hyperphagia." (PMID 29959379, 2018). "A study reported that an obese leptin-deficient girl with hepatic steatosis exhibited rapid improvement after the introduction of recombinant leptin therapy." (PMID 28643267, 2018). "Leptin deficiency causes morbid obesity with fatty liver in mice and humans, and can lead to chronic liver disease." (PMID 30424542, 2018).
Hepatic steatosis (continued). "Diabetic KK-A, leptin-resistant (db/db) and leptin-deficient (ob/ob), high fat and high fructose diet-fed mice all of which exhibit hepatic steatosis, have all been reported to demonstrate impeded regeneration after hepatectomy or CCL4 administration." (PMID 28129776, 2017). "Our results suggest that mSJH exerts an anti-hepatic steatosis effect via activation of leptin and associated signaling cascades related to lipid metabolism." (PMID 28358008, 2017). "In turn, the loss of leptin signaling in liver has been associated with hepatic steatosis and higher TG incorporation into VLDL particles." (PMID 28744221, 2017). "As discussed further below, adipokines including leptin and adiponectin are implicated in the development of fatty liver disease and treatment with either leptin or adiponectin reversed alcohol-induced fatty liver." (PMID 28212318, 2017). "There was no strong evidence of associations between birth weight, cord leptin, and lipids with ultrasound-diagnosed fatty liver." (PMID 27648968, 2016). "Metformin crosses the placenta and has been associated with decreased inflammation and reversal of fatty liver in obese leptin-deficient mice." (PMID 27555877, 2016). "It has been shown that increased Nrf2 activity is associated with a higher level of hepatic steatosis in leptin-deficient obese mice." (PMID 25738756, 2015). "In line with the observed excess adiposity and hepatic steatosis, leptin-deficient mice exhibited higher Pparg mRNA levels in the adipose tissue and liver that were reduced by leptin replacement and, to a lesser extent, by caloric restriction." (PMID 26159457, 2015). "Animal models of fatty liver disease can arise as a result of induced genetic mutation and most published studies have employed the leptin-resistant (db/db) mouse." (PMID 26508982, 2015). "Previous studies similarly showed that serum leptin levels are associated with IR and hepatic steatosis." (PMID 24524410, 2014). "A role for IL-18 has been postulated in the development of hepatic steatosis since both serum IL-18 concentration and hepatic Il18 mRNA expression are elevated in lipopolysaccharide-treated leptin deficient ob/ob mice and high fat diet fed-C57BL/6 mice." (PMID 25251155, 2014). "Leptin deficiency in mice and humans causes morbid obesity with fatty liver, and replacement leads to decreased food intake and increased energy expenditure." (PMID 24822223, 2014). "Normalizing plasma adiponectin or leptin level was associated with attenuation of alcoholic fatty liver." (PMID 23405143, 2013). "We have previously demonstrated in leptin-deficient ob/ob mice that AMP-DNM treatment reduced liver steatosis associated with a restoration of liver insulin signaling." (PMID 23056165, 2012). "In mice, trans-10, cis-12 CLA causes severe lipodystrophy reducing the levels of leptin and adiponectin, which leads to hepatic steatosis." (PMID 21869929, 2012). "This study aimed to assess a possible association between circulating leptin levels and ultrasound metrics of liver steatosis and fibrosis, measured with FibroScan, in a cohort of individuals that are overweight or obese and free from concomitant chronic comorbidities and pharmacological treatments." (PMID 40507178, 2025). "Although leptin-deficient ob/ob mice have been investigated to determine whether hepatic steatosis promotes susceptibility to hepatotoxic insults, carbon tetrachloride (CCl4)-induced hepatic fibrosis in ob/ob mice remains largely unknown." (PMID 39832399, 2025). "Furthermore, elevated leptin levels have been linked to the worsening of hepatic steatosis, as leptin activates the JAK2/STAT3 pathway, increasing the expression of the suppressor of SOCS3, which contributes to hepatic lipid accumulation." (PMID 40862455, 2025). "Additionally, increased plasma bilirubin levels were found to improve fatty liver disease and blood glucose levels in leptin‐deficient obese mice." (PMID 39582374, 2025).
Hepatic steatosis (continued). "Furthermore, FGF-1 has demonstrated its ability to improve DM-induced hepatic steatosis in leptin-deficient ob/ob mice through its anti-inflammatory function." (PMID 38542166, 2024). "T2D remission was associated with a lower leptin–adiponectin ratio, hepatic steatosis and triglycerides, a trend towards greater exercise capacity and significantly lower minute ventilation/carbon dioxide production (VE/VCO2 slope) vs. active T2D (27.74 ± 3.95 vs. 30.52 ± 5.46, p < 0.0025)." (PMID 37233158, 2023). "Studies have shown that Lepr functionality is critical to diabetes control, and may be a factor in liver complications, as leptin resistance has been associated with the pathogenesis and progression of T2D, hepatic steatosis and fibrosis." (PMID 36737598, 2023). "This was caused by impairment of the leptin-signal transduction mediated by both janus-activated kinase-2 and the mitogen-activated protein kinase pathway, leading finally to hypertriglyceridemia and hepatic steatosis." (PMID 37999226, 2023). "Based on these findings from previous studies and our results, it is possible that changes in histidine levels caused by the SNL diet could influence histamine/leptin signaling and lead to the improvement of hepatic steatosis." (PMID 38085726, 2023). "Furthermore, leptin indicates a predisposition to metabolic disorders, including fatty liver diseases." (PMID 36899958, 2023). "We also observed that the Tmem135 mutation ameliorates fatty liver disease in leptin mutant mice." (PMID 36599953, 2023). "Although leptin acts as an anti-steatotic hormone preventing the accumulation of and promoting the mobilization of hepatic lipids, leptin resistance may cause the leptin inability to alleviate hepatic steatosis." (PMID 36009862, 2022). "In this model, leptin deficiency modulates inflammation independently of hepatic steatosis." (PMID 35392825, 2022). "However, surprisingly, CLA alleviated hepatic steatosis in leptin-deficient ob/ob mice, which was reversed by the presence of leptin." (PMID 35382379, 2022). "Indeed, mice lacking NKT cells were shown to be more susceptible to developing fatty liver, and leptin-deficient mice displayed reduced hepatic steatosis after adoptive transfer of NKT cells." (PMID 33578800, 2021). "Moreover, rosiglitazone, a PPARγ agonist, promoted mitochondrial dysfunction, oxidative stress, and liver steatosis in leptin-deficient mice." (PMID 33383845, 2020). "Leptin deficiency causes morbid obesity and fatty liver disease in mice and humans." (PMID 30424542, 2018). "Leptin and adiponectin are among the primary adipokines measured and accordingly, several investigations have implicated these adipokines in the development of alcoholic lipodystrophy and hepatic steatosis." (PMID 28212318, 2017). "In addition to the excess energy intake model, an ob/ob (leptin-deficient) mouse model was employed in this study to evaluate the role of hepatic TRAF3 in genetically induced hepatic steatosis." (PMID 26882989, 2016). "In fact, metformin treatment reversed fatty liver disease in obese leptin-deficient mice." (PMID 27555877, 2016). "In contrast, serum levels of AIM may not be correlated with IR as assessed by HOMA-IR, but adipocytokines were associated with IR and insulin sensitivity, and serum levels of leptin were associated with hepatic steatosis." (PMID 24524410, 2014). "However, in genotype 1, hepatic steatosis was associated with host factors such as leptin levels, BMI, percentage of BF, and visceral obesity." (PMID 20712878, 2010). "Furthermore, melatonin reverses leptin methylation and expression, which are closely associated with hepatic steatosis, and reduces inflammation and chronic hepatic steatosis without apoptosis or histone deacetylation in prenatally dexamethasone-exposed livers with steatosis in young rats." (PMID 37886973, 2023).
Hepatic steatosis (continued). "It has been hypothesized that, as soon as hepatic steatosis progresses, leptin release may cause the death of macrophages and hepatocytes through CD8+ T lymphocytes, which could in turn promote the proliferation and invasiveness of tumors such as thyroid cancer." (PMID 37965446, 2023). "Besides alcohol, other drugs and medical treatments can also damage the liver by an alteration in leptin secretion, causing changes in lipid homeostasis that could lead to fatty liver disease, steatohepatitis and even cirrhosis." (PMID 33316927, 2020). "Moreover, leptin administration reverses alcohol-induced lipid accumulation in liver, and leptin deficiency contributes to the pathogenesis of alcoholic fatty liver via modulation of AMPK and STAT3 signaling, implying the protective role of leptin from alcoholic liver disease." (PMID 29312618, 2017). "The univariate analyses revealed that sex, pre-therapy BMI, C3 levels, and hepatic steatosis were associated with pre-therapy leptin levels, whereas the multivariate analysis showed that sex, pre-therapy BMI, and C3 levels were independently associated with the pre-therapy leptin levels." (PMID 27870883, 2016). "Moreover, at a later stage, leptin may cause hepatic steatosis to turn into steatohepatitis by amplifying selected proinflammatory responses." (PMID 26569494, 2015). "Furthermore, the marked hepatic steatosis has been observed in leptin-deficient ob/ob mice." (PMID 23476686, 2013). "While reduction of plasma leptin level is likely a factor mediating the interaction of zinc deficiency and ethanol in induction of fatty liver, elevation of gut permeability and plasma endotoxin level may account for the synergistic action in induction of hepatic inflammation." (PMID 24155903, 2013). "In HFD-fed mice, JH01 reduced body weight gain, serum triglyceride and total cholesterol levels, improved ALT and AST levels, decreased leptin concentrations, and attenuated hepatic steatosis." (PMID 41977396, 2026). "Under physiological conditions, leptin reduces hepatic lipogenesis and promotes fatty acid oxidation, thereby protecting against hepatic steatosis." (PMID 40956476, 2025). "Post-mortem analyses included qPCR, Western Blotting, biochemical and microscopical assessments for hepatic steatosis and insulin resistance, hypothalamic and adipose tissue inflammation, and circulating lipid, leptin and IL-6 levels." (PMID 39754229, 2025). "BB supplementation was able to control weight gain, leptin and adiponectin levels, and hepatic steatosis, as well as reduce oxidative stress." (PMID 40847538, 2025). "Leptin plays a protective role in preventing ectopic fat accumulation and lipotoxicity, and leptin resistance is considered a significant factor in the progression of fatty liver." (PMID 40336965, 2025). "Imbalanced adipokines, such as reduced adiponectin and elevated leptin, also contribute to hepatic steatosis and inflammation." (PMID 40626217, 2025). "A strong positive correlation was observed between hepatic steatosis area (under the Oil Red-O analysis) and leptin (r=0.7941, P=0.0002)." (PMID 40862455, 2025). "Elafin was found to upregulate miR-181b-5p and miR-219-5p in serum exosomes from livers of HFD-fed mice, which led to increased leptin expression in adipose tissue, alleviating hepatic steatosis." (PMID 40129979, 2025). "This approach, which avoids arbitrary cut-offs while preserving the biological relationship between leptin and adiposity, demonstrated a clear dose-response relationship with hepatic steatosis." (PMID 40956476, 2025). "This inflammation, marked by imbalanced TNF-α, IL-6, adiponectin, and leptin, promotes hepatic steatosis and IR, a core NAFLD pathogenesis." (PMID 41334428, 2025). "Recent studies have shown that leptin promotes hepatic lipid export, thereby protecting against hepatic steatosis." (PMID 40956476, 2025).